TPTEP2 (TPTE pseudogene 2)
Synonyms: Z98749.2
Gene: Transcribed unprocessed pseudogene on chromosome 22 (38,361,381 to 38,384,096, reverse strand). Ensembl gene ENSG00000244627.
Diseases named in the same sentence as TPTEP2 in open-access papers:
TPTEP2 is named in the same sentence as 1 disease in open-access papers, as found by Europe PMC text mining. Sharing a sentence is not in itself a finding about the gene and the disease. The quoted sentences say what the papers report.
tumor (1 paper, 2024). "Furthermore, eight target genes (COL4A3, FAM30A, FCRL5, MDM4, SYNE2, TNFRSF13C, TPTEP2, VAMP1) were systematically positively correlated with ESR2 expression patterns in tumor types with low ESR2 expression as a prognostic factor concerning OS or DFS." (PMID 39201394, 2024). "Notably, our findings highlight seven genes (FAM30A, MDM4, POU2AF1, SYNE2, TNFRSF13C, TPTEP2, VAMP1) presenting positive correlations with ESR2 expression patterns in all tumor types with high ESR2 expression as a positive prognostic factor with regard to OS or DFS." (PMID 39201394, 2024).